CAT (catalase)
Diseases named in the same sentence as CAT in open-access papers (continued):
Sharing a sentence is not in itself a finding about the gene and the disease.
psoriasis (continued). "Enhancing catalase activity and alleviating oxidative stress may have potential in the management of psoriasis and the reduction of skin inflammation." (PMID 39456475, 2024). "It has been found that psoriasis development is associated with a reduction in the total antioxidant status (TAS) of plasma connected with cellular deficiencies in antioxidant enzyme activity, especially in the case of catalase (CAT)." (PMID 37150149, 2023). "An assessment by Gabr and Al-Ghadir detected notable negative association of malondialdehyde and nitric oxide, as well as positive correlations of total antioxidant status, superoxide dismutase and catalase (p < 0.001) with different forms of psoriasis (mild, moderate, severe)." (PMID 35204165, 2022). "Moreover, psoriasis patients have been shown to have decreased levels of the antioxidant enzymes superoxide dismutase and catalase and, conversely, elevated levels of the oxidative stress marker malondialdehyde, compared with control subjects." (PMID 34565327, 2021). "Furthermore, marked increases were observed in the blood MDA levels of patients with psoriasis, whereas blood antioxidant levels, including β-carotene, vitamin E, catalase, and GPx, were reduced." (PMID 34639139, 2021). "In particular, multiple studies have shownsignificant aberrations of OS parameters in psoriasis patients, and most showmarked decreases in the antioxidant enzymes catalase (CAT), superoxide dismutase(SOD), and glutathione peroxidase (GSH-Px) in psoriatic lesions and in matched serumsamples." (PMID 29630472, 2018). "Therefore, the use of CAT activity or expression as a therapeutic approach might provide new possibilities for the treatment of psoriasis and the management of oxidative stress-related pathways involved in the illness." (PMID 39456475, 2024). "The only result that was of note was the observation that blood selenium levels were significantly lower for carriers of the CC variant of SOD2, CAT, and DMGDH, which may be a generalized effect of these polymorphisms and the association between Se and psoriasis." (PMID 38791044, 2024). "Therefore, the combination of SOD and/or catalase with L-NAME may represent a novel treatment strategy for psoriasis." (PMID 34639139, 2021). "Natural products exert anti-oxidant effect in psoriasis by enhancing the enzymatic activity of key antioxidants, including superoxide dismutase (SOD), glutathione (GSH), and catalase (CAT)." (PMID 40690118, 2025). "In patients with active psoriasis, the levels of antioxidant enzyme levels, particularly SOD and CAT, are often reduced, indicating an impaired antioxidant defense system." (PMID 40731925, 2025). "Quercetin, a flavonoid found in many vegetables and fruits like apples and onions, has been shown to exert a powerful anti-oxidant effect in imiquimod-induced psoriasis, by increasing the activity of SOD, CAT, and GSH, as well as, decreasing MDA accumulation." (PMID 40690118, 2025). "The reduction of other prototypical examples of redox signaling-mediated antioxidative enzymes is also involved in the pathomechanism of psoriasis, such as GSH, Px, CAT, and SOD." (PMID 36242051, 2022). "Spleen index increased as did proinflammatory marker expression (IL-17, IL-23, MDA, and ROS), whereas expression of redox regulators (SOD, CAT, and GSH) decreased in the psoriasis-like model." (PMID 35720176, 2022). "After a month of therapy, normalisation was observed in terms of CAT and SOD activity in granulocytes and epidermal cells affected by psoriasis, as compared to the control group of psoriasis patients receiving placebo." (PMID 32575706, 2020). "Several TFs/uDBPs additionally showed altered expression in blood from psoriasis patients (increased: JUNB, STAT3, DTL, CAT; decreased: CUX2, ZNF559, AVEN, RUVBL1, RAN)." (PMID 25883770, 2015). "CAT activity was lower in patients with psoriasis, and therapeutic procedures did not significantly change it, except for MTX, which further reduced CAT activity." (PMID 38540199, 2024).
psoriasis (continued). "Subsequently, research was conducted to evaluate the level of oxidative stress in individuals with psoriasis by quantifying the presence of malondialdehyde (MDA) in their blood serum as an oxidant, as well as assessing the activity of erythrocyte CAT as an antioxidant." (PMID 39456475, 2024). "In this way, catalase and SOD from ATCC12228EVs could contribute to the reduction of ROS in psoriasis." (PMID 34884834, 2021). "A large number of studies indicated that using various compounds with antioxidant effects to increase the content of SOD, CAT, and GSH and eliminate ROS could effectively alleviate the symptoms of psoriasis." (PMID 33323018, 2021). "In addition it has been found that the activity of blood CAT increased, and activity of blood SOD decreased with increasing severity of psoriasis." (PMID 27377373, 2016). "In our study, however, PCs could shift this unequilibrium; namely, PCs remarkably increased the levels of antioxidants, e.g. SOD, CAT, and GSH, and decreased the expression of oxides and inflammatory factors like IL-17, IL-23, ROS, and MDA in the psoriasis-like cells." (PMID 36178125, 2022). "The relevance of oxidative stress in psoriasis has not been demonstrated definitively, but psoriasis patients show increased levels of oxidative stress markers, decreased levels of antioxidant molecules, and reduced activity of main antioxidant enzymes, such as superoxidase dismutase and catalase." (PMID 34748530, 2021).
viral infection (38 papers, 2013 to 2025). "Catalase activity is higher in both cultivars, which suggests the plants are actively fighting the oxidative stress caused by the viral infection." (PMID 37507984, 2023). "The metabolic response of CA seems to be particularly affected by severe CTV isolates, since both T36 and T318A affected the flavonoid biosynthesis and SOD and CAT antioxidant enzyme activity, and this may explain the susceptibility of different citrus species to viral infections." (PMID 36987082, 2023). "Taken together, the persistent accumulation of H2O2, despite catalase activation, suggests that ROS production exceeds detoxification capacity under the combined influence of heat and viral infection." (PMID 41012677, 2025). "Spectrophotometric measurement of catalase activity revealed a slight increase in enzyme activity under thermal stress (30 °C, 37 °C) or viral infection when compared to the control." (PMID 41012677, 2025). "Viral infection caused depletion of most of the assessed enzymes like SOD, MnSOD, CAT, and GR in liver tissue compared to the control mice, whereas the GPx and GST activities measured in liver tissue were significantly higher in the norovirus-infected mice." (PMID 38612426, 2024). "During Chinese wheat mosaic virus infection, the TaTHI2 protein accumulates to facilitate ROS production by suppressing TaCPK5‐mediated activity of the catalase protein TaCAT1, limiting viral infection." (PMID 39658820, 2024). "Mechanically, P31 attenuates the expression of salicylic acid (SA)-responsive pathogenesis-related genes (PR) by inhibiting catalase activity to allow for efficient viral infection." (PMID 37112970, 2023). "The interaction between the helper component proteinase (HCPro) of chilli veinal mottle virus (ChiVMV) and the catalase (CAT) of N. benthamiana, induces a ROS burst to facilitate viral infection." (PMID 38093999, 2023). "Several recent studies have shown that viral proteins promote viral infection through different mechanisms by interacting with catalase." (PMID 37112970, 2023). "The ROS levels were increased after viral infection as expected, it was potently suppressed in the cells that were treated with lycorine or catalase (CAT), a ROS scavenger." (PMID 35928150, 2022). "Viral infections also enhance the production of oxidants and prevent the synthesis of CAT, SOD, and GSH-Px, resulting in the disruption of the redox balance, leading to a weak immune response, and promoting viral infection." (PMID 35891451, 2022). "Although providing quercetin orally simultaneously with viral installation did not restore the decrease in the level of vitamin E connected with a viral infection, it augmented the pulmonary levels of superoxide dismutase, reduced glutathione, and catalase." (PMID 33195565, 2020). "Under virus infection and treated plants, CAT activity was increased and interact with the virus, especially certain virus elements, such as CMV 2b protein." (PMID 32429524, 2020). "The decreased protein levels of both SOD2 and CAT due to virus infection indicated a decreased capability to counteract ROS production, which is in agreement with the finding that the virus infection stimulated ROS overproduction." (PMID 31011285, 2019). "In the present study, we found that drought stress significantly increased the activities of SOD, POD, and CAT in both the healthy and diseased plantlets, but single virus infection increased slightly the activity of antioxidant enzymes." (PMID 27313542, 2016). "In our observation, the advantage of NAC treatment or Cu/Zn SOD and catalase expression in blocking-B2 function is greater than the effects on whole viral infection." (PMID 25008790, 2014). "Moreover, enzymes such as glutathione and catalase are related to the increased production of this molecule during viral infections, a crucial object of study for future investigations." (PMID 36680261, 2023).
viral infection (continued). "The severity of plant symptoms was positively correlated with ToCV accumulation, suggesting that the interaction between ToCV p27 and CAT may play an essential role in virus infection and pathogenicity." (PMID 37112970, 2023). "In addition, HCPro-OX plants exhibited reduced CAT activity and accumulated a high level of virus compared with WT plants at the early stage post-viral infection." (PMID 32594157, 2020). "SOD1, SOD3, catalase, and Nrf2 were downregulated by viral infection." (PMID 26761025, 2016). "After PR8 infection, however, CAT activity in the lungs of male mice dropped substantially, reaching levels on p.i. days 3 and 6 that were significantly lower than those of the female group, which remained stable throughout the viral infection (unpaired t-test *p-value <0.05)." (PMID 30105026, 2018). "Streptomyces can improve the activity of plant antioxidant enzymes (SOD, CAT, POD, and MDA), assisting plants in resisting viral infections." (PMID 38357345, 2024). "Plant cells defend themselves against the oxidative damage caused by ROS through the production of antioxidant enzymes, such as SOD, POD, CAT, MDA, and PAL, which play important roles in plant defense against pathogens and counteract viral infection." (PMID 39049860, 2024). "Then, HCPro interacts with CAT1 to inhibit CAT activity, resulting in the generation of H2O2, which aids in virus infection." (PMID 37112970, 2023). "We found that transcript abundance of catalase and glutathione-S-transferase (GST), enzymes mediating oxidative stress responses to viral infection in Ae. aegypti, were significantly downregulated in co-infected cells compared with DENV2 single-infected cells." (PMID 37165438, 2023). "CAT, which has the same effect as APX, was inhibited during viral infection, and ROS species in plants were increased, while the expression of SA and PR pathway genes were reduced." (PMID 38093999, 2023). "Then, HCPro interacted with CAT1 to inhibit CAT activity, resulting in H2O2 generation to aid virus infection." (PMID 32594157, 2020). "The expression of antioxidant enzymes including superoxide dismutase 1 (SOD1), SOD2, catalase (CAT), and glutathione peroxidase 4 (GPX4) was differentially affected following the virus infection." (PMID 31011285, 2019). "In other models of experimental viral infections (influenza), exogenous treatment with the AOE catalase significantly reduced viral titers in the lung of mice." (PMID 29740449, 2018). "These better physiological conditions persist during viral infection when we observed: upregulation of enzymes responsible for GSH biosynthesis, higher level of PRDX1, maintenance of CAT activity, and a less decrease of GSHPx activity." (PMID 30105026, 2018). "SOD, CAT, GPX and APX were over-expressed due to viral infection indicating their role in detoxification of ROS." (PMID 28324587, 2013). "In our studies, a significant enhancement of SOD (273 %), CAT (98 %), GPX (106 %) and APX (104 %) activities was observed in the infected plant parts, accompanied with increased H2O2 formation during viral infection." (PMID 28324587, 2013). "As it was known that many biocontrol bacteria and pathogens can induce a plant defense response to fungal, bacterial, and viral diseases, in the present study, the enzymatic activities of POD, SOD, and CAT in the roots of the cucumbers induced by ZF129 and infected with F. solani were examined." (PMID 40282240, 2025). "Moreover, viral infections themselves can dysregulate redox balance, contributing to persistent H2O2 accumulation despite elevated catalase activity." (PMID 41012677, 2025). "Catalase activity and mRNA expression analysis indicated that Hdh-CAT might regulate the antioxidant defense system against thermal stress, viral infection, bacterial infection, starvation, and cadmium-induced toxicity." (PMID 36670971, 2023).
viral infection (continued). "Additionally, to perform a systemic analysis of H2O2 scavenging enzymes in response to viral infection, APX and catalase expression levels were evaluated in infected tobacco plants at 7, 9, 11, 14, and 21 dpi." (PMID 37655790, 2023). "In other animal models of pulmonary diseases, including asbestos- and radiation-dependent pulmonary fibrosis, hyperoxia, hydrogen peroxide-mediated injury, and viral infection with influenza H1N1, catalase treatment has also been shown to be effective in modulating clinical illness." (PMID 32107411, 2020). "In addition, we found that virus infection broadly affected the expression of the antioxidant enzymes such as SOD1, CAT, GPX4, and SOD2 at both mRNA and protein levels." (PMID 31011285, 2019). "In addition, serum antibody titers of viral diseases as well as serum enzyme activity of AST, ALT, CAT, and SOD were significantly changed by Q10 treated groups than controls (P≤0.01)." (PMID 30863780, 2019). "Here, we found that the virus infection significantly decreased the protein levels of both SOD2 and CAT at the late stage of infection (16 h after infection), which may compromise their capacity of converting O2−· into H2O2 in the mitochondrial matrix as well as detoxifying H2O2 in the cytosol." (PMID 31011285, 2019).
Anxiety (37 papers, 2010 to 2026). Intense feelings of nervousness, tension, or panic often arise in response to interpersonal stresses. "In this recent study, an increase in the concentration of pro-inflammatory cytokines (TNF-α and IL-1β), inhibition of antioxidants enzymes (CAT, SOD) and GSH were associated with anxiety-like behaviour in diabetic rats treated with HAART." (PMID 35769902, 2022). "Meanwhile, regarding the catalase result, a prior study discovered that CAT over-expression reduced anxiety in mice conducting the zero maze task." (PMID 32962160, 2020). "SOD and CAT activity strongly and positively correlated with the indicator of decreased anxiety level expressed as CDOA (r = 0.73 and 0.70, p = 2.1−6 and 6.2−6 respectively)." (PMID 31861240, 2019). "Behavioral test parameters for anxiety and spatial memory were assessed followed by biochemical parmeters (lipid peroxidation, super oxide dismutase, catalase, glutathione peroxidase, reduced glutathione, etc.)subsequently." (PMID 21713134, 2010). "Various behavioral tests parameters for anxiety, locomotor activity and nociceptive threshold were assessed followed by biochemical assessments (malondialdehyde level, glutathione, catalase, nitrite and protein) subsequently." (PMID 20459658, 2010). "The prenatal VPA‐induced autism model increased nociceptive threshold, heightened anxiety‐like behaviors, impaired balance power, delayed spatial learning, elevated malondialdehyde, and decreased glutathione and catalase levels in the brains of the male offspring." (PMID 39910830, 2025). "Moreover, it was found that bergamot essential oil improved symptoms of stress-induced anxiety by enhancing the activities of GPx, CAT and SOD in the hippocampus and the frontal cortex." (PMID 36358502, 2022). "The prenatal VPA‐induced model of autism resulted in heightened NT, increased anxiety‐like behaviors, compromised balance, delayed spatial learning, elevated malondialdehyde levels, and reduced GSH and CAT levels in the brains of male offspring." (PMID 39910830, 2025). "Cotreated mice demonstrated improved memory, reduced anxiety and depressive‐like behavior, and enhanced antioxidant systems, as evidenced by normalized SOD, CAT, and GPx and lowered MDA and AChE activity." (PMID 41394883, 2025). "Previous reports have also demonstrated that the administration of antioxidants, such as resveratrol and ascorbic acid, attenuates acute stress-induced anxiety by increasing the activity of antioxidant enzymes, such as SOD, GPx, and CAT." (PMID 33922431, 2021). "Our findings are supported by a previous study demonstrating that AGOM treatment decreased the release of cytokines (TNF-α, IL-6 and IL-1β) and restored BDNF levels and the activity of the antioxidant enzymes CAT and GPx in the brain in an HFD-induced anxiety-like behavior model." (PMID 40076566, 2025). "Previous animal research has demonstrated that the upregulation of catalase even in the absence of alteration in markers of oxidative stress can enhance cognition and reduce measures of anxiety." (PMID 39004753, 2024). "In addition, chamomile decoction ameliorated high fat diet-induced anxiety of rats through suppression of lipoperoxidation, and promoting antioxidant enzyme activities of SOD, CAT and GPx." (PMID 36358502, 2022). "In this study, HAART-AgNPs alleviates the anxiety-like behaviours in the diabetic rats via improved metabolic disturbances and anxiogenic parameters in the open field, which correlated with reduced MDA and improvement in GSH, CAT and SOD." (PMID 35769902, 2022). "The effects of the aqueous extract of B. hispida fruit on the anxiety-induced zebrafish’s SOD and CAT focus on the antioxidant effects of SOD, which converts free radicals into oxygen and hydrogen peroxide, and the catalase activity, which indirectly reduces anxiety." (PMID 38541704, 2024).
Anxiety (continued). "Moreover, it was found that a red pomegranate fruit extract-based formula could improve the anxiety-like behaviors via decreasing the level of MDA and promoting the activities of nitric oxide synthase, SOD and CAT." (PMID 36358502, 2022). "Ameliorated social deficits without affecting locomotion or anxiety and restored oxidative stress markers (SOD, CAT) in hippocampus and cerebellum." (PMID 41155624, 2025).